ENSG00000252290
Gene: Small nucleolar RNA gene on chromosome 1 (237,555,040 to 237,555,171, reverse strand). Ensembl gene ENSG00000252290.
Homologues: Paralogues in human: SNORA25 (65% identical), SNORA25B (65% identical).